ENSG00000277809
Gene: Miscellaneous RNA gene on chromosome 2 (44,935,585 to 44,935,908, forward strand). Ensembl gene ENSG00000277809.
Gene Ontology:
Biological process: regulation of gene expression